RELN (reelin)
Diseases named in the same sentence as RELN in open-access papers (continued):
Sharing a sentence is not in itself a finding about the gene and the disease.
brain disorder (11 papers, 2012 to 2024). A disease affecting the brain or part of the brain. "This implies that de novo insertion of L1 into RELN and DAB1, the key molecules in the Reelin signaling pathway, can cause various brain disorders such as ASD and SZ." (PMID 36143463, 2022). "The association between ADAMTS2 and reelin could explain ADAMTS2’s association with multiple brain diseases but further mechanistic studies are clearly required." (PMID 35557837, 2022). "Of particular importance is understanding how Reelin signaling is turned off because inhibition of such a mechanism would strengthen Reelin signaling and may help improve brain disorders caused by diminished Reelin function." (PMID 32161359, 2020). "After discussing the shared and distinct elements of the Reelin signaling pathway involved in neuronal migration, dendritic growth, spine development and synaptic plasticity, I briefly outline the data revealing the importance of Reelin in human brain disorders." (PMID 32604886, 2020). "Finally, I will briefly outline the data revealing the importance of Reelin in human brain disorders." (PMID 32604886, 2020). "In addition, in several brain disorders, including AD, Reelin protein levels, its post-translational modifications, and Reelin proteolytic processing are found to be dysregulated." (PMID 23082219, 2012).
infection (9 papers, 2009 to 2025). The state of being infected such as from the introduction of a foreign agent such as serum, vaccine, antigenic substance or organism. "In the short term, loss of pickle enhances expression of RelN target genes, significantly boosting the host defense from infection with pathogenic bacteria." (PMID 27631699, 2016). "To study the physiological relevance of Pickle in selectively inhibiting RelN homodimers, we examined the response of pickle mutants to infection with the pathogenic bacteria L. monocytogenes (L.mono) and P. rettgeri (P.ret)." (PMID 27631699, 2016). "RELN was upregulated in Suffolk (susceptible) compared to Texel (resistant) animals three days post infection with T. circumcincta." (PMID 25074012, 2014). "In accordance with the human data, plasma Reelin expression started to increase around days 3-4 of infection and remained elevated during the course of the experiment." (PMID 37441066, 2023). "These two mechanisms are key in acute and long COVID, suggesting a role for Reelin in this infection." (PMID 37441066, 2023). "In almost a decade of work with Reelin conditional KO mice and Reelin-depleting agents, we have not observed any increased susceptibility of Reelin-depleted mice to inflammatory diseases or infection." (PMID 38607022, 2024). "Furthermore, this study demonstrates that anti-Reelin treatment dampens the severity of the infection in a preclinical model." (PMID 37441066, 2023). "The average Reelin concentration was increased two-fold in the serum of the mild COVID group and five-fold in the severe COVID group, suggesting that Reelin expression increases with the severity of the infection." (PMID 37441066, 2023). "Interestingly, loss of pickle hyper-activated AttD and Defensin only when these AMPs were driven solely by RelN, such as following infection with L.mono (AttD and Defensin) and P.ret (AttD)." (PMID 27631699, 2016).
adenocarcinoma (1 paper, 2022). A common cancer characterized by the presence of malignant glandular cells. "Regarding adenocarcinomas, reelin mRNA levels were higher in the adjacent tissues than in either healthy colons or adenocarcinomas." (PMID 36290310, 2022). "In addition, reelin mRNA abundance in polyps or adenocarcinomas in mouse colons is lower and higher than in their adjacent tissues, respectively." (PMID 36290310, 2022). "Therefore, the expression levels of reelin together with those of ApoER2 could contribute to the difference between the two types of adenocarcinomas." (PMID 36290310, 2022). "DNMT-1 and ApoER2 might downregulate reelin expression in both types of adenocarcinomas." (PMID 36290310, 2022).
benign tumor (1 paper, 2017). "Reelin was well expressed in our study involving nevocellular nevi – i.e., benign tumor with risk of malignant transformation." (PMID 28255385, 2017).
heart disease (1 paper, 2024). "It would also be valuable to evaluate whether treatment with Reelin reduces susceptibility to develop depressive symptoms, heart disease, and cognitive dysfunction in the context of healthy aging and in the context of future stress exposure(s)." (PMID 38482060, 2024).
kidney disease (1 paper, 2017). "Moreover, Ang II facilitated the reelin expression and Dab1 phosphorylation in vivo and in vitro, indicating that reelin and Dab1 were involved in kidney disease and podocyte injury." (PMID 28676854, 2017).
metabolic disease (1 paper, 2021). A congenital disorder (due to inherited enzyme abnormality) or acquired (due to failure of a metabolically important organ) disorder resulting from an abnormal metabolic process. "The amyloid precursor protein (APP), down regulated in the SS LCL is included in the TGFβ signaling WikiPathway, the Reelin signaling in neurons IPA canonical pathway, and IPA network 4 for hereditary disorder, metabolic disease, organismal injury and abnormalities." (PMID 33669496, 2021).
RELN also shares sentences with these, for which no sentence is quoted: multiple myeloma (4 papers); multiple sclerosis (4); behavioral disorders (3); cerebellar ataxia (3); Down syndrome (3); genetic disorder (3); hypertrophy (3); Lissencephaly type 2 (3); mood disorder (3); age-related macular degeneration (2); Atrophy (2); cardiovascular disease (2); cognitive delay (2); Dandy-Walker malformation (2); dyslexia (2); frontotemporal dementia (2); muscle-eye-brain disease (2); non-small cell lung carcinoma (2); osteoarthritis (2); rectal cancer (2); retinal degeneration (2); amyotrophic lateral sclerosis (1); ankylosing spondylitis (1); anxiety disorder (1); arteriosclerosis (1); astrocytoma (1); attention deficit-hyperactivity disorder (1); benign prostatic hyperplasia (1); brain malformations (1); breast tumors (1).
A further 49 diseases each share a sentence with RELN in 1 paper.